FGF1 (fibroblast growth factor 1)
Diseases named in the same sentence as FGF1 in open-access papers (continued):
Sharing a sentence is not in itself a finding about the gene and the disease.
Obesity (continued). "FGF1 could affect the UPR pathway in models of obesity and MASLD, even after the chronic ER stress conditions that dampen the potential of the pathway had manifested in the liver." (PMID 41541501, 2026). "Together, these data indicate that FGF1 treatment can promote metabolic changes in cancer cells that may sustain their growth and highlight the potential to define FGF1-dependent gene expression signatures that predict endocrine resistance in obesity." (PMID 37608351, 2023). "In women with obesity who are experiencing weight gain, locally produced FGF1 may activate ER to promote cancer cell metabolic reprogramming and tumor progression independently of estrogen." (PMID 37608351, 2023). "Notably, FGF2 and to a lesser extent, FGF1, were each more highly expressed in CAFs compared to distant fibroblasts, but the distant fibroblasts from women with obesity had greater FGF2 expression than the lean group." (PMID 37800138, 2023). "Adipocyte-mediated expression of FGF-1, the ligand for FGFR-1, is elevated under conditions of obesity in mice and humans, suggesting that adipocytes may contribute to endocrine resistance through upregulation of FGF-1." (PMID 35435599, 2022). "FGF1, a multi-pleiotropic metabolic regulator, is known to modulate blood glucose in metabolic diseases, including type 2 diabetes, non-alcoholic fatty liver, and obesity." (PMID 34025437, 2021). "However, the precise FGF1 regulated signalling cascades related to obesity‐induced inflammation and systemic insulin resistance are yet to be elucidated." (PMID 32979037, 2020). "In conclusion, our data suggest that FGF1 expression may be one genetic determinant behind an individual's tendency to resist obesity and/or metabolic disease even when consuming a diet high in saturated fats." (PMID 30972920, 2019). "In addition, interaction between endogenous TAK1 and TAB1 was strongly inhibited in the liver of FGF-1 treated obesity- or TNF-α-induced insulin resistance mice." (PMID 31866871, 2019). "Our prior studies implicated adipose-derived FGF1 in the obesity-driven growth of ER-positive breast tumors; therefore, we hypothesized that altered signaling downstream of FGF1 may influence the differential responses of tumors to estrogen deprivation in the context of obesity." (PMID 37608351, 2023). "Finally, although FGF1 administration may negatively impact behavior, our results show that it is a promising approach to the treatment of obesity and metabolic disease." (PMID 30972920, 2019). "The positive correlation of genes such as HSD11B1, PTPN22, ABCC1, MMP9, FGF1, and F13A1 with M0 and M1 macrophages suggests a possible role in shaping the immune response toward a more beneficial phenotype in obesity." (PMID 39594522, 2024). "This suggests that the combination of obesity and overfeeding/weight gain after OVX enhances adipose production of FGF-1, which can be blunted by preventing weight gain during the post-OVX period." (PMID 35725493, 2022). "Further exploration of mechanisms of FGF1 regulation of adipose development and metabolism in response to dietary stress may provide an experimental framework linking the incidence and treatment of obesity and related pathologies to the status of FGF1 gene expression in humans." (PMID 30972920, 2019). "To investigate the potential protective effects of FGF-1 on insulin resistance, we treated HFD-induced obesity mice with 0.1 mg/kg FGF-1 every day for 4 weeks." (PMID 31866871, 2019). "In the present study, we investigated the effects of administering recombinant FGF-1 to obesity- or TNF-α-induced insulin resistance mouse models, and our findings indicated that FGF-1 significantly improves insulin resistance and reduces inflammation." (PMID 31866871, 2019).
Obesity (continued). "Several gene sets that were positively enriched with obesity were also enriched in FGF1-treated MCF7 TAMR cells, including glycolysis, suggesting that obesity supports an environment of endocrine therapy resistance in ER-positive breast cancer, potentially prior to treatment." (PMID 37608351, 2023). "Together with the differences in total and phospho-proteins detected in untreated cells or with E2 or FGF1, our data suggest a complex alteration in protein signaling dynamics in ER-positive breast tumors that can grow without estrogen in obesity." (PMID 37608351, 2023). "FGF1 also plays vital roles in lipid metabolism through the FGF1/FGFR1 signaling pathway and may aid in obesity prevention." (PMID 34306666, 2021). "Notably, in men with obesity and DM2, the genes up-regulated due to bright light include fibroblast growth factor 1 (FGF1), vasorin (VASN), ribonuclease A family member 1 (RNASE1), pappalysin 1 (PAPPA), Interleukin 7 (IL7), and fatty acid binding protein 3 (FABP3)." (PMID 40981208, 2025).
Insulin resistance (26 papers, 2015 to 2026). Increased resistance towards insulin, that is, diminished effectiveness of insulin in reducing blood glucose levels. "Genetic inactivation of FGF1 expression was associated with impaired glucose tolerance, insulin resistance, increased gluconeogenesis, and hepatic steatosis in DIO models." (PMID 41072794, 2025). "Insulin resistance, adipose inflammation, and tumor-promoting growth factors such as fibroblast growth factor 1 (FGF1) are closely associated with most cancer progression." (PMID 36141228, 2022). "Previous studies reported that Fgf1-deficient mice developed insulin resistance under HFD conditions." (PMID 36235710, 2022). "Similar to the in vitro results, knocking out adipocyte mTORC2/Rictor led to the loss of FGF1 function in controlling Ccl2 expression and ameliorating insulin resistance." (PMID 32979037, 2020). "Loss of FGF1 leads to deleterious changes in adipose morphology, metabolism, and insulin resistance." (PMID 30972920, 2019). "However, the underlying molecular mechanism whereby FGF-1 inhibits insulin resistance remains poorly understood." (PMID 31866871, 2019). "However, the underlying molecular mechanism whereby FGF-1 represses insulin resistance remains largely unknown." (PMID 31866871, 2019). "Our results show that reduced HS sulfation and impaired HS production via Ndst1 and Ext1 inactivation in AT, respectively, promote glucose intolerance and insulin resistance by attenuating the endogenous FGF1-metabolic activity." (PMID 41072794, 2025). "In the event of insulin resistance, the anti-lipolytic activity of FGF1 holds increasing importance as an alternative method of glucose and lipid homeostasis." (PMID 41072794, 2025). "According to the recent studies, FGF1 not only improves insulin resistance through regulating JNK pathway, but also subsequently performs other functions to treat diabetic complications." (PMID 33788387, 2021). "Studies in recent years have reported that FGF1 inhibits inflammatory level, then ameliorates diabetic nephropathy and improves insulin resistance through regulating JNK pathway." (PMID 33788387, 2021). "Using GTT and ITT, we had further confirmed that FGF1 treatment had remarkably lowered fasting glucose level, remitted impaired glucose tolerance and insulin resistance." (PMID 32460803, 2020). "Our results further confirmed the therapeutic potential of FGF1 for insulin resistance and type 2 diabetes." (PMID 32194395, 2020). "Further, we developed a model that genetically induced the adipocytes‐specific mTORC2/Rictor‐knockout (AdRiKO) obese mice to understand the role of mTORC2/Rictor in mediating FGF1 on adipose tissue inflammation and insulin resistance." (PMID 32979037, 2020). "When the FGF1-KO mice are challenged with a high-fat diet for 16 weeks, they develop severe glucose intolerance and insulin resistance." (PMID 32372975, 2020). "Further, we demonstrate the key role of the adipocyte mTORC2/Rictor in mediating the effect of FGF1 on adipose tissue inflammation and systemic insulin resistance." (PMID 32979037, 2020). "Recent studies have reported the characteristic of insulin resistance in FGF1 knockout mice fed on a high‐fat diet (HFD)." (PMID 32979037, 2020). "Previous studies have shown that FGF1 has therapeutic potential for insulin resistance and type 2 diabetes." (PMID 32194395, 2020). "Based on these findings, we suggested that the metabolic effects of FGF1 on adipose tissue inflammation and systemic insulin resistance occurred by inhibiting the transcription and expression of Ccl2 in eWAT." (PMID 32979037, 2020). "Studies using human samples have reported both a positive correlation of FGF1 serum levels with insulin resistance as well as inverse correlations of FGF1 with BMI and blood triglycerides." (PMID 32372975, 2020). "Taken together, we present that FGF1 alleviates systemic insulin resistance by inhibiting macrophage recruitment and inflammatory responses in adipose tissues." (PMID 32979037, 2020).
Insulin resistance (continued). "Our results demonstrated that FGF1‐induced amelioration of insulin resistance in obese mice was related to the decreased levels of pro‐inflammatory adipose tissue macrophages (ATMs) and plasma inflammatory factors." (PMID 32979037, 2020). "In this article, we presented evidence that FGF1 ameliorated adipose tissue inflammation and insulin resistance." (PMID 32979037, 2020). "Mechanistically, we found that FGF-1 improves insulin resistance and inflammation accompanied by attenuation of the c-Jun N-terminal kinase signaling pathway." (PMID 31866871, 2019). "Mechanistically, FGF-1 attenuates inflammation and insulin resistance through blocking the TAK1/TAB1 interaction." (PMID 31866871, 2019). "Our findings also expand the knowledge of physiological functions of FGF-1 in insulin resistance and suggest inhibition of inflammation as an attractive therapeutic strategy for the treatment of insulin resistance." (PMID 31866871, 2019). "In summary, the present study confirms the protective effects of FGF-1 in DIO- or TNF-α-induced insulin resistance mice." (PMID 31866871, 2019). "Further, FGF-1 treatment significantly represses TNF-α-induced insulin resistance in vitro and in vivo." (PMID 31866871, 2019). "In this study, we observed that administration of FGF-1 improved insulin resistance as well as metabolic disorder." (PMID 31866871, 2019). "To further assess the role of FGF-1 in TNF-α-induced hepatic insulin resistance in vivo, we injected FGF-1 into wild-type mice treated with TNF-α." (PMID 31866871, 2019). "Here, we sought to delineate the role of FGF-1 in insulin resistance with respect to its anti-inflammatory capability." (PMID 31866871, 2019). "These integrative physiological observations indicate that FGF-1 is an essential growth factor for attenuating insulin resistance and metabolic disorder." (PMID 31866871, 2019). "It has been shown that FGF-1 plays a key role in nutrient homeostasis, and Fgf-1-/- mice develop severe insulin resistance after HFD feeding." (PMID 31866871, 2019). "We observed that FGF-1 treatment significantly improved insulin resistance in TNF-α-induced insulin resistance in vitro and in vivo." (PMID 31866871, 2019). "Subsequent experiments demonstrated that FGF-1 ameliorated insulin resistance, and inflammation was accompanied by decreased c-Jun N-terminal kinase (JNK) signaling." (PMID 31866871, 2019). "Several observations provide evidence that FGF-1 treatment significantly improved insulin resistance." (PMID 31866871, 2019). "Mechanistically, FGF-1 ameliorated insulin resistance and inflammation was accompanied by decreased JNK signaling." (PMID 31866871, 2019). "Although known as a mitogenic factor, exogenous administration of FGF1 results in potent and insulin-dependent glucose lowering effect in insulin resistance mice." (PMID 31920680, 2019). "The anti-FGF1 antibody group represented diminished expression levels of insulin resistance markers in comparison to the CM-treated group." (PMID 30445954, 2018). "Most recently, a breakthrough has been made in the use of FGF1 as a therapeutic agent for the treatment of insulin resistance and type-2 diabetes." (PMID 26161641, 2015). "Therefore, in the present study, we explored the possible molecular mechanism by which FGF1 ameliorates adipose inflammation and systemic insulin resistance." (PMID 32979037, 2020). "Future studies should however explore whether other factors, such as adiponectin, T lymphocytes, B lymphocytes and exosomes, are involved in the FGF1 regulation of adipose inflammation and insulin resistance." (PMID 32979037, 2020). "Therefore, the FGF1‐regulated signalling pathways involved in systemic inflammation, as well as the molecular mechanism by which FGF1 ameliorates insulin resistance, deserve further exploration." (PMID 32979037, 2020).
Insulin resistance (continued). "In this study, we found that FGF-1 had positive effects on glucose intolerance, hepatic lipid accumulation, and insulin resistance, while it markedly repressed cytokine secretion (TNF-α and IL-6) in serum and reduced liver inflammation in diet-induced obesity (DIO) mice." (PMID 31866871, 2019). "Next, we explored the mechanisms of the protective action of FGF-1 against insulin resistance." (PMID 31866871, 2019). "Therefore, we next examined the effects of FGF-1 on mice treated with TNF-α to induce insulin resistance." (PMID 31866871, 2019). "However, when fed a high-fat diet (HFD), Fgf-1-/- mice developed an exaggerated diabetic phenotype, accompanied by severe insulin resistance and marked inflammation." (PMID 31866871, 2019). "To test whether FGF-1 attenuates TNF-α-triggered insulin resistance, we next investigated the role of FGF-1 in TNF-α-induced hepatic insulin resistance." (PMID 31866871, 2019). "Moreover, added an anti-FGF1 neutralizing antibody to the cAT-MSC CM treated insulin resistance model." (PMID 30445954, 2018). "We added anti-FGF1 neutralizing antibody to the CM-treated insulin resistance models." (PMID 30445954, 2018). "Interestingly, the IPA upstream regulator analysis also highlighted the effect of the Triacylglycerol Degradation pathway on the activity of the FGF1 growth factor, a known player for hepatic and peripheral insulin resistance." (PMID 29326659, 2017). "Because deficiency of FGF1 in mice exacerbated high-fat diet-induced diabetic phenotypes, such as insulin resistance and defects in adipose remodeling in gonadal white adipose tissue, FGF1, may directly and/or indirectly act on bone." (PMID 25873956, 2015). "FGF1 is another secreted protein that has been shown to dampen hepatic glucose output by suppressing adipose lipolysis, improve systemic insulin sensitivity by reducing adipose inflammation, and alleviate hepatic steatosis, inflammation, and insulin resistance." (PMID 37961647, 2025). "Therefore, FGF1 may be a latent new aim for the treatment of insulin resistance and T2DM in the future." (PMID 39296548, 2024). "However, the protective effect of FGF-1 in insulin resistance have not been fully understood." (PMID 31866871, 2019). "In contrast NRG1, FGF1 and IVM bind to site 2, but act as inhibitors of site 2-mediated pro-inflammatory action and insulin resistance (see Section 1)." (PMID 40943574, 2025). "Together, these data indicate that overexpression of endothelial FGF1 not only reduces adiposity, but also confers protection against HFD‐induced insulin resistance." (PMID 30972920, 2019). "Since we suspected FGF1 would have a role in this effect, we measured FGF1 concentrations in cAT-MSC CM and added an anti-FGF1 neutralizing antibody into CM-treated 3T3-L1 insulin resistance models and assessed alterations of glucose uptake levels." (PMID 30445954, 2018). "However, injection of FGF-1 similarly reduced HFD-induced glucose and insulin levels and improved insulin resistance under fasting conditions, which eliminated the effect of individual body weight on insulin sensitivity." (PMID 31866871, 2019). "This implied that FGF1 did not ameliorate insulin resistance in obese AdRiKO mice." (PMID 32979037, 2020). "Thus, we speculate that the anti-inflammatory effect of FGF-1 is strong and able to block inflammation in TNF-α-induced insulin resistance, resulting in similar protective effects in both models." (PMID 31866871, 2019). "Moreover, unlike PBS-injected DIO mice, the insulin resistance index HOMA-IR of FGF-1-treated mice was markedly decreased." (PMID 31866871, 2019).